NOX4 (NADPH oxidase 4)
Diseases named in the same sentence as NOX4 in open-access papers (continued):
Sharing a sentence is not in itself a finding about the gene and the disease.
tumor (continued). "In many tumors, ROS has also been proved to degrade and remodel the tumor extracellular matrix through TGF-β1, hypoxia, NOX4 and other mechanisms." (PMID 36424540, 2022). "Compared to that in the control group, the tumor size of the NOX4 + NTC group was significantly larger, but this effect was markedly abrogated by FOXM1 knockdown (NOX4 + shFOXM1 group)." (PMID 34740322, 2021). "Accordingly, silencing NOX4 conferred an advantage to the human HCC cells, resulting in the earlier onset of tumor formation and an increase in tumor size in xenograft mice." (PMID 34571961, 2021). "We have shown that NOX4 is an important regulator of TGF-β1 mediated myCAF activation and that NOX4 inhibition can reduce ECM deposition and CAF-mediated tumour cell invasion and migration." (PMID 34262652, 2021). "A 2019 study demonstrated that IP4 plays a critical role in redox homeostasis upon cisplatin exposure by reducing cisplatin-induced ROS through inhibition of a ROS-generating enzyme, NADPH oxidase 4 (NOX4), which promotes cisplatin-resistant tumor growth." (PMID 34925435, 2021). "In ovarian cancers, NOX4-derived H2O2 regulates HIF-1α expression which in turn governs VEGF levels, essential for tumor-induced angiogenesis." (PMID 34205998, 2021). "Six tumor antigens (THBS2, FSTL3, TNNT1, BGN, CTHRC1, and NOX4) were identified as potential therapeutic candidates for the anti-CRC mRNA vaccine that can be processed and presented by APCs to activate a robust immune response." (PMID 35127707, 2021). "NOX4, as a key gene for VM formation in GBC, is highly expressed in the tumor and stroma, which is related to the progression and poor prognosis of GBC patients." (PMID 33153467, 2020). "NOX4 is highly expressed in GBC and its stroma, which is the key gene for VM formation, and is correlated with tumor aggression and survival of GBC patients." (PMID 33153467, 2020). "In the tumor cells of GBC, NOX4 was highly expressed in 50 cases (58.8%) and low in 35 cases (41.2%); in stromal cells, the expression of NOX4 was high in 55 cases (64.7%) and low in 30 cases (35.3%)." (PMID 33153467, 2020). "In the tumour microenvironment, cancer cells produce high levels of ROS deriving from mitochondrial dysfunction, upregulation of NADPH oxidase 1 (NOX-1) and NADPH oxidase 4 (NOX-4), and alterations of antioxidant enzymes." (PMID 29967776, 2018). "Nox4 is one of the nicotinamide adenine dinucleotide phosphate (NADPH) oxidases (NOXs) family and is the most frequently expressed isoform in these tumor cells." (PMID 30513726, 2018). "Nox4 promoted cell proliferation via activation of the GLI1 pathway and overexpression of GLI1 reversed the suppression of tumor cell growth induced by silencing NOX4." (PMID 30513726, 2018). "Using this model, we tested the efficacy of inhibiting NOX4 for preventing myofibroblastic CAF accumulation and tumor progression." (PMID 28922779, 2018). "Suppression of Nox4 was found to revert the myofibroblastic-CAF phenotype, prevent myofibroblastic-CAF accumulation and slower tumor proliferation." (PMID 30513726, 2018). "Using a xenograft model from tuberin-null tubular cells in nude mice, both anti-sense Nox4 and GKT137831, a specific inhibitor of Nox1/4, significantly inhibited the tumor growth." (PMID 29491408, 2018). "At the second day, we administered anti-sense Nox4, sense Nox4 oligonucleotides or PBS and the tumor growth was monitored." (PMID 29491408, 2018). "To determine the effect of the anti-sense Nox4 in vivo, we subcutaneously inoculated LEF2 (Tsc2−/−) cells to generate tumor xenografts in nude mice." (PMID 29491408, 2018).
tumor (continued). "A highly statistically significant positive correlation was found between NOX4 and eigengenes for the ECM module and TGF-β-activated/myofibroblast gene signature in each individual tumor type (Pearson’s r > 0.8, adj." (PMID 28922779, 2018). "Therefore, NOX4 might be a promising target for anti-angiogenic tumor therapy." (PMID 28594389, 2017). "Inhibition experiments with siRNA constructs showed that Nox4 is specifically needed for metastasis and also for epithelial to mesenchymal transition (EMT), a process needed for invasiveness of tumor cells mediated by regulating the actin cytoskeleton." (PMID 28620580, 2017). "Therefore, NOX4 may act as a tumour suppressor at different levels." (PMID 27941881, 2017). "The STAT5 activity as a tumor suppressor is attributed mainly to the control of reactive oxygen species through the expression of PUMA, BIM, and NOX4." (PMID 28740570, 2017). "To explore the mechanism underlying the functional interplay of NOX4 and IL-6 in enhancing A549 tumor growth and survival of NSCLC cells in vivo, we sought to determine the reciprocal activation between NOX4/Akt and IL-6/STAT3 signalings in vivo." (PMID 25504436, 2015). "More importantly, Nox4 knockdown in GBM cells decreased the levels of VEGF expression and tumor induced angiogenesis." (PMID 24868315, 2014). "Besides, NOX4 depletion could significantly prolong the survival time of tumor-harbored mice." (PMID 24946933, 2014). "Cycling hypoxia-induced ROS via Nox4 is a critical aspect of cancer biology to consider for therapeutic targeting of cycling hypoxia-promoted HIF-1 activation and tumor progression in GBM." (PMID 21935366, 2011). "In contrast, tumor-derived NOX4-produced hydrogen peroxide induces M2 polarization through HIF-1α stabilization, creating chemokine gradients (CCL7/IL-8) that recruit CCR1+ immunosuppressive macrophages to support tumor progression." (PMID 40733095, 2025). "Pharmacological inhibition of NOX4 using GKT137831, an oral drug developed as an anti-fibrotic agent, abrogated TGFβ-dependent ROS production, myofibroblast transdifferentiation, and slow tumor growth." (PMID 40469190, 2025). "Surprisingly, despite the absence of NOX4 in stromal cells, tumours from WT and NOX4-/- mice were identical in size and in the expression levels of Krt19, α-Sma (Acta2) and collagen 1 (Col1a1)." (PMID 40820091, 2025). "Targeting individual ROS pools or their generating enzymes, like NOX4 or mitochondrial SOD2, may offer strategies to disrupt tumor-specific signaling while minimizing systemic redox disruption." (PMID 40801639, 2025). "Pharmacological NOX4 inhibition (GKT137831) disrupts this axis—reducing CAFs’ contractility and MDSC infiltration—which synergizes with anti-PD1 therapy to reverse T cell exclusion and improve tumor regression." (PMID 40733095, 2025). "To bypass the undesired effects of TGF-β inhibitors on tumour cells, we decided to switch strategies and search for downstream mediators specific to TGF-β pro-tumorigenic actions, focusing our attention on NOX4, which is highly increased in iCCA compared to normal tissue." (PMID 40820091, 2025). "Furthermore, it has been verified that NOX4 and TGFB2 exhibit elevated expression levels in tumor tissues relative to normal tissues." (PMID 39314752, 2024). "Knock-down of AQP3 in HeLa cell line attenuated the entry of NOX4-derived H2O2 into the cells induced by TGF-β1 and the migration and invasive capacity of HeLa cells, and which was confirmed by the nude mouse xenograft tumor model." (PMID 38230207, 2024). "Furthermore, CCL22 has been found to stimulate DGKα activity in tumor cells, suppressing NADPH oxidase 4 (NOX4) and averting cisplatin-induced ROS overproduction." (PMID 39286635, 2024). "While 5 genes were downregulated in tumor tissues, including PLAT, ERBB2, CEACAM1, NOX4, and UCHL1." (PMID 37056778, 2023).
tumor (continued). "Moreover, in non-tumor hepatocyte, such as HepaRG cells, NOX1 and NOX4 are even lower (at least by an order of magnitude); however, in these, DUOX2 is readily detected." (PMID 37189460, 2023). "Because the difference in the expression of the same gene is small in patients, the relative differential expression of mRNA is not a major factor that leads to the major role of NOX4 in the tumor immune microenvironment." (PMID 36874093, 2023). "Our research concluded that NOX4 knockdown could prevent EMT in HCC cells, boost antitumor immune effects, and overcome sorafenib resistance for tumor inhibition." (PMID 37626693, 2023). "In NSCLC, NOX4 blockade by GKT137831 could reduce pro-tumoral M2-like macrophage and immune infiltration to limit tumor growth." (PMID 35646942, 2022). "Of note, we also found that NOX4 expression positively correlated with HIF1α (resistant marker), Glut1 and LDHA (glycolytic markers), and Ki67; whereas it negatively correlated with Bcl2 in tumor tissues in patients with PTC." (PMID 35396551, 2022). "Furthermore, it is very interesting to note that induction of CHAC1 and NOX4, two genes significantly induced by NCX4040, have been suggested to be biomarkers for ferroptosis-related cell death in tumor cells." (PMID 36612280, 2022). "NOX4, the most frequently expressed member of NOX family, thus has a potential role in activating diverse signaling pathways and mediating metabolic plasticity through manipulating tumoral ROS level to participate in tumor occurrence and development." (PMID 35646942, 2022). "Because each cancer has distinct criteria for its clinical grade, we analyzed NOX4 mRNA expression patterns by tumor types and not in a Pan-Cancer manner." (PMID 33557266, 2021). "Furthermore, FRGs, IRGs, DEGs, and genes in the blue module were intersected, and seven hub genes (JUN, TNFAIP3, NOX4, HMOX1, SOCS1, CYBB, and TFRC), related to both ferroptosis and tumor immunity, were obtained." (PMID 35174170, 2021). "Interestingly, tumoral NOX4 has also been shown to recruit M2 tumor-associated macrophages via ROS signaling to promote cancer growth, suggesting that NOX inhibitors could also have the potential to induce indirect anti-cancer effects by modulating the tumor immune microenvironment." (PMID 33799550, 2021). "Thus, these xenograft models demonstrated that IFI6 promotes ESCC tumor growth in vivo, and again demonstrated a critical role of IFI6 in mitochondrial Ca2+, OXPHOS efficiency and ATF3/NOX4 axis." (PMID 32727517, 2020). "Furthermore, depletion of NOX4, ANGPTL4, MMP-1, and MMP-9 in CRC cells significantly blocked OA-enhanced metastatic seeding of tumor cells in lungs." (PMID 32641980, 2020). "Consistent with the in vitro results, caffeine significantly inhibited G6PDH enzymatic activity, p-STAT3 signaling activation, and cyclin E, NOX4, and p47-phox (NOX2 regulatory subunit) protein expression, and upregulated the expression of SOD2 protein, in xenografted RCC tumor tissues." (PMID 33123534, 2020). "Immunohistochemistry showed parallel expression of NOX4 and TRPM2 in all 73 tumor samples examined." (PMID 31671815, 2019). "Second, we did not explore the comprehensive mechanisms of Nox4 and downstream pathways, nor investigate how Nox4 overexpression promotes tumor cell proliferation, invasion and metastasis." (PMID 30513726, 2018). "At present, there are no known pharmacological inhibitors that are specific for Nox4; however, such a substance would be highly desirable for a new concept of tumor therapy." (PMID 30084091, 2018). "Thus employing a specific inhibitor of Nox4, GKT, showed a significant reduction in the tumor burden in the xenograft model by inhibiting tumor cell proliferation." (PMID 29491408, 2018).
tumor (continued). "Most studies of NOX4 in malignancy have focused on the evaluation of a small number of tumor cell lines and not on human tumor specimens themselves; furthermore, these studies have often employed immunological tools that have not been well characterized." (PMID 28578276, 2017). "As expected, we also observed that knockdown of NOX4 significantly decreased the glucose uptake and lactate production levels, but increased the OCR in the primary culture cells derived from subcutaneous xenograft mice tumour tissue." (PMID 28232723, 2017). "Importantly, NOX4 gene deletions are frequent in HCC patients, correlating with higher tumour grade." (PMID 27941881, 2017). "IHC staining showed suppression of NOX4 by shRNA or the inhibitor DPI also displayed lower cell proliferation indices (Ki67-positive) and higher cell apoptosis (TUNEL-positive) compared with control tumours." (PMID 28232723, 2017). "According to these data, NOX4 and DUOX1/2 exhibit a tumour suppressive function." (PMID 28894215, 2017). "Several studies have demonstrated that served as the main producer of ROS in RCC, NOX4 suppression could abrogate RCC cells proliferation, invasion, colony formation, and tumor growth." (PMID 29312589, 2017). "Furthermore, the functional interplay of NOX4 and IL-6 in enhancing growth and survival of NSCLC cells in vivo was also confirmed by Ki67 (the biomarker to evaluate tumor proliferation) and TUNEL staining analysis (evaluation of tumor apoptosis)." (PMID 25504436, 2015). "As for all the oxidative tumor cells tested in this study, they did express Nox1, Nox2, and Nox4 but did not activate the NF-κB pathway in response to lactate." (PMID 26528183, 2015). "NOX4 is likely to be involved in these effects, since silencing of NOX4 significantly inhibited basal ROS production, reduced FAKY397 phosphorylation and decreased tumor cell viability." (PMID 24911159, 2014). "Especially for NOX4, it was the most frequently expressed NOX isoform in several tumor cell lines." (PMID 24946933, 2014). "Our results also indicate that Nox4 is a critical mediator of these processes and its expression tends to occur in potential cycling hypoxic areas with HIF-1 activation and blood perfusion within the endogenous tumor microenvironment." (PMID 21935366, 2011). "In summary, Nox4 knockdown and Tempol treatment during GBM progression may be a therapeutic approach to block the impact of cycling hypoxia on tumor progression." (PMID 21935366, 2011). "The NOX4 expression level was not correlated to pathological parameters such as grade, stage, and tumor size." (PMID 22032647, 2011). "And no matter whether with tumor metastasis, differentiation or neurorecidivism, didn’t seem to affect NOX4 expression in tumor." (PMID 36874093, 2023). "Based on GO and KEGG pathway enrichment analysis, we found that NOX4 and its co-expressed mRNA exhibited enrichments for signaling pathways such as PI3K/AKT, TGF-β, MAPK signaling and many more, which were connected with the tumor immune evasion as well as the occurrence of tumors." (PMID 36249057, 2022). "The importance of uncovering signaling interactions between NOX4 and AMPK was also highlighted by data demonstrating that the pharmacological activation of AMPK suppresses mitochondrial oxidation and primes mitochondria apoptosis, leading to lessened tumor burden of acute myeloid lymphoma in mice." (PMID 35269843, 2022). "NOX4-induced ROS regulate a variety of signaling pathways including PI3K/Akt, NF-κB, and STAT3, which may promote growth, metastasis and chemoresistance of tumor cells." (PMID 36670929, 2022).
tumor (continued). "NOX4 induction by TGF-β may mediate some of its suppressor effects, such as apoptosis or senescence: it has been shown that TGF-β induces senescence in hepatocellular carcinoma cells and inhibits tumor growth." (PMID 34205678, 2021). "We also showed that NOX4 inhibition could reverse TGF-β1 mediated CAF activation, leading to reduced extra-cellular matrix (ECM) deposition, increased CD8+ T-cell infiltration into tumours and improved immunotherapy efficacy." (PMID 34262652, 2021). "The expression of these three target genes is also positively correlated with the degree of immune cell infiltration in the gastric cancer tumor microenvironment, suggesting that NOX4, COL8A1 and CHST1 may be involved in the establishment of the tumor immune microenvironment." (PMID 33193668, 2020). "In a follow-up study, the authors showed that NOX4 (NADPH oxidase subunit 4) was a critical mediator of radio resistance exerted by cyclic hypoxia (0.5–1% O2, 10 min hypoxia, 10 min reoxygenation, 12 cycles) in glioblastoma cell lines, GBM8401 and U251 and tumor models." (PMID 31382593, 2019). "In addition, these cell lines were also treated with a Nox4 inhibitor (GKT-137831) and the results showed GKT-137831 could inhibit the proliferation of OTSCC tumor cells in a dose-dependent manner." (PMID 30513726, 2018). "The lack of plasma membrane localized NOX4, furthermore, suggests that efforts to evaluate ROS generation in tumor biology should focus on tools that measure intracellular ROS, including fluorescent dyes, and DNA damage markers (i.e. anti 8-oxoguanine antibodies)." (PMID 28578276, 2017). "We propose that Nox4 downregulation by DNA methylation could favor the proliferation of cancer cells during different stages of HCG; accordingly, Nox4 could act as a potential tumor suppressor gene in normal rat liver." (PMID 27895046, 2017). "Because these alterations in the mRNA and protein expression levels are not observed in untreated rats, Nox4 may function as a tumor suppressor in liver." (PMID 27895046, 2017). "Not just limited to tumor cells, we see that MEF Nf2−/− cells support elevated levels of NOX4 and DUOX2 compared to MEF Nf2fl/fl." (PMID 33410252, 2021). "In both established tumor cell lines that the authors (HepG2 and SH-SY5Y), the enzyme, Nox4, was strongly expressed as compared with non-tumorous material from the same organ, and located in the ER, like the yeast enzyme." (PMID 30084091, 2018). "We conclude that NOX4-mediated mtROS signaling increases MMP9 mRNA stability and affects cancer invasiveness but not tumor growth." (PMID 30281903, 2018). "Moreover, as Nox4 positivity is not observed homogeneously throughout the tumor microenvironment, these observations lead us to hypothesize that high Nox4 expression is not a general reactive stromal marker but may reflect/define a particular onco‐supportive CAF subtype." (PMID 29441570, 2018). "Briefly, even though NOX4 appears to be upregulated by Bezielle in tumor cells, partial silencing of its expression in MDAMB231 cells indicated that NOX4 produced ROS do not play a significant role in cell death induced by Bezielle." (PMID 22319564, 2012). "The transdifferentiation of fibroblasts into CAFs is dependent on the delayed phase of intracellular ROS production by NADPH oxidase 4 (NOX4), and this transdifferentiation may be independent of TGF-β signaling to promote tumor progression." (PMID 36422541, 2022).